IDO1 (indoleamine 2,3-dioxygenase 1)
Diseases named in the same sentence as IDO1 in open-access papers (continued):
Sharing a sentence is not in itself a finding about the gene and the disease.
tumor (continued). "Importantly, while selective IDO1 inhibition attenuated CR tumor growth, it concomitantly upregulated the TDO2 enzyme." (PMID 37226257, 2023). "While CD40-stimulating immunotherapy can enhance anti-tumor responses by activating DCs and increasing T-cells priming, TECs increase Indoleamine 2, 3-dioxygenase 1 (IDO-1), which has an immunosuppressive feedback mechanism that inhibits the response to such immunotherapy." (PMID 37666809, 2023). "The enhanced anti-tumor immune responses achieved with IDO1 inhibitor treatment suggested that induction of IDO1 activity may be selected for as a means for tumors to escape immune surveillance." (PMID 37182174, 2023). "Therefore, the abnormally high expression of IDO1 is closely related to tumor immune escape and is an important target for tumor immunotherapy." (PMID 37190515, 2023). "Moreover, pharmacologic inhibition of IDO1 with 1-MT not only reduced tumor growth but also increased STING level and activation under cisplatin, RT, or diABZI treatment." (PMID 37670034, 2023). "IDO1 inhibitors and radiation may cooperatively suppress tumor proliferation through the alterations in the Wnt/β-catenin pathway, cell cycle, and immune response." (PMID 36653774, 2023). "Therefore, IDO1 inhibitors have a prospect for development as potential drugs for tumor immunotherapy." (PMID 37334368, 2023). "The kyn pathway is closely related to the tumor immune escape mechanisms, with the prerequisite for this process being that kynurenic acid is synthesized by IDO1.Thus, microbes can directly and indirectly control tryptophan metabolism through multiple integrated pathways." (PMID 37999261, 2023). "Therefore, the research and development of IDO1 inhibitors are of great importance for tumor therapy." (PMID 37509627, 2023). "Within the cohort, tumour tissue from 22 participants were assessed for IDO1 expression." (PMID 37041200, 2023). "IDO1 induction in malignant cells and their microenvironment has also been hypothesised as a key mechanism to modulate anti-tumor immune response, helping in escaping immune surveillance." (PMID 36879122, 2023). "Through investigating the tumor immune microenvironment, IDO1 was found to be a metabolic enzyme that could mediate tumor immune evasion and a potent immunomodulator." (PMID 37408559, 2023). "In addition, kynurenine acts via AHR to degrade the adhesion molecule E-cadherin, resulting in enhanced tumor invasion, which is reduced by 1-MT, probably consistent with a role for IDO1 or IDO2." (PMID 37296860, 2023). "However, when comparing IDO1 inhibition to dual inhibition (red line), it was evidenced that dual inhibition was more potent than selective IDO1 inhibition alone in reducing tumor growth and tumor weight of CR tumors (B—red)." (PMID 37226257, 2023). "The fact that radiomics can predict the HOT/COLD status is an interesting issue because it implies that the tumor images may reflect specific information about PD-L1 and IDO1 expression as well as TCD8 infiltration and activation of the IFN-gamma pathway." (PMID 37492391, 2023). "Given Kyn production via IDO1, we used 1-MT, an IDO1 inhibitor, to treat tumor-bearing mice." (PMID 37919525, 2023). "The resulting effect deriving from the combination of the catalytic inhibition and the enhancement of the signaling function of IDO1 may strongly depend on the cell type (i.e., tumor and/or immune cell populating the tumor microenvironment)." (PMID 37122718, 2023). "We speculate that nodes of IDO1+ cells, either tumor cells themselves, or infiltrating myeloid cells, can propagate ferroptosis suppression within the TME." (PMID 35245456, 2022). "IDO1 is an immune regulatory gene that was shown to recruit and activate myeloid-derived suppressor cells through a Treg-dependent mechanism that contributed to aggressive tumor growth and poor response to T-cell targeted therapy." (PMID 35690832, 2022). "IDO1-expressing MDSCs are involved in tumor immunosuppression and immune escape processes." (PMID 35681736, 2022).
tumor (continued). "Consistently, immunoblotting and real-time RT-PCR results showed that both protein and mRNA expression of IDO1 were significantly higher in the tumor tissues of stages II and III compared to that in normal lung tissues, and that it was highest in stage III tumors." (PMID 35187162, 2022). "IDO1 mediates tumor immune escape via three main downstream pathways." (PMID 36408235, 2022). "Similarly, IDO1 can promote AHR-driven processes and is associated with worse outcomes for tumor patients." (PMID 35778697, 2022). "Finally, IDO1 modulates the expression of interferon-γ and interleukin-6, thereby promoting tumor neovascularization." (PMID 36545214, 2022). "In contrast, W>Y substitutions showed neither enrichment in number, nor association to tumours or IDO1 expression." (PMID 35264796, 2022). "Thus, it is imperative to further explore the immunosuppressive mechanism mediated by indoleamine 2,3-dioxygenase 1 in the tumor microenvironment to optimize clinical trial treatment strategies." (PMID 35681736, 2022). "However, the high tumor HPV-antigen load results in a high expression of immune checkpoint genes on tumor cells (e.g., indoleamine 2, 3-dioxygenase 1, IDO-1), and in dysfunction of HPV-specific CTL." (PMID 36123711, 2022). "Moreover, the correlated expression of IDO1 and collagen genes synergistically enhances tumor cell migration and invasion in vivo and in vitro." (PMID 35203450, 2022). "Firstly, 11 tumor types were included in this study and the role of IDO1 in different tumors may be inconsistent." (PMID 36212460, 2022). "The activation of AhR accelerates the conversion of effector T lymphocytes into regulatory T cells, and then may upregulate IDO1 expression in DC cells, expanding immunoregulatory effects and blocking anti-tumor immune response of the body further." (PMID 35563059, 2022). "Tumor cells lead to NK cell dysfunction by promoting IDO1 expression." (PMID 35681736, 2022). "Furthermore, concomitantly delivered NLG919 will inhibit indoleamine 2,3-dioxygenase 1 (IDO-1), resulting in immune response reactivation for fighting primary and distant tumors by remodeling the immunosuppressive tumor microenvironment (ITM)." (PMID 34983555, 2022). "Then, we further detected the IDO1 in tumor tissues of NSCLC patients." (PMID 35872931, 2022). "Moreover, IDO1 supports tumor angiogenesis, antagonizing the anti-angiogenic effect of IFN-γ and favoring tumor immune escape." (PMID 36551630, 2022). "Accordingly, TECs express IDO1 to accelerate tumor neovascularization and promote tumor growth." (PMID 35681736, 2022). "Indeed, preclinical models targeting IDO1 strongly enhanced B16 and 4T1 tumor response to both anti-CTLA4 and anti–PD-1 therapy, and demonstrated efficacy regardless of tumor IDO1 expression." (PMID 35040434, 2022). "The results represent a novel mechanism of activating immunosuppressive IDO1 and inducing kynurenine generation which, together with the production of inflammatory cytokines, would contribute to tumour initiation and progression, providing a new target for drug development." (PMID 35371018, 2022). "Additionally, immune checkpoint genes such as BTLA, CTLA4, CD96 and IDO1 were enriched on the tumor side of the interface." (PMID 36313703, 2022). "Early studies have shown that IDO1 can promote tumor immune escape." (PMID 35872931, 2022). "Hence, MDSCs, Tregs and DCs coordinate to form the tumor immunosuppressive environment through the IDO1 pathway." (PMID 35681736, 2022). "Similarly, in colon cancer, the silencing of IDO1 inhibits the expression of β-catenin in the nucleus, as well as the expression of Axin2 and Cyclin D1, further exerting an inhibitory effect on tumor proliferation." (PMID 36358792, 2022). "Intriguingly, the individual components of TME that constitute the tumor immunosuppressive network may be IDO1 expression-dependent." (PMID 35681736, 2022).
tumor (continued). "In addition, compound 14b significantly inhibited tumor growth comparable to the antitumor activity of erlotinib and the IDO1 inhibitor epacadostat in murine tumor models." (PMID 36034879, 2022). "Therefore, IDO1-mediated tryptophan metabolism assists tumor cells in forming an immunosuppressive TME." (PMID 36163134, 2022). "Evidence that tumours co-opt a similar mechanism to suppress the endogenous immunity of the host, followed from demonstrations that the enzyme is expressed by a broad range of clinical tumours and that IDO1 expression by experimental murine tumours prevented their rejection in pre-immunized mice." (PMID 36145311, 2022). "Iinrodostat potently and specifically inhibits IDO1 to block an immunosuppressive mechanism that could be responsible for tumor escape from host immune surveillance with favorable PK/PD characteristics that support clinical development." (PMID 36358940, 2022). "NK cells dysfunction mediated by IDO1 impedes the body’s normal anti-tumor immune response." (PMID 35681736, 2022). "Thus, IFN-gamma shows a conflicting role in tumor immunity, being the main IDO1 inducer but also involved in preventing new blood vessels formation during tumor growth." (PMID 35408802, 2022). "In addition, studies have shown that IDO-1 can induce immunosuppression and promote tumor progression in LC animal models." (PMID 35872931, 2022). "In vivo antitumor studies shown that compound 14b could significantly inhibit the expression of IDO1 in mice with 4T1 tumor cells, as a result inhibited the tumor growth." (PMID 36034879, 2022). "In addition, tryptamine, the indole derivative, inhibits the enzyme indoleamine 2,3-dioxygenase (IDO1), which is involved in tumor immune tolerance." (PMID 35784338, 2022). "IDO1 is overexpressed in tumor cells and antigen-presenting cells (APC)." (PMID 36304470, 2022). "Our study reveals the molecular mechanism of IDO1 post-translational modification, which might represent a feasible tumor-targeting strategy and an alternative immunotherapy method to directly inhibiting IDO1." (PMID 36163134, 2022). "IDO1 is widely expressed in human macrophages and dendritic cells, which has attracted great attention from pharmaceutical academia and industries in the field of tumor immunotherapy." (PMID 35677437, 2022). "Indoleamine 2, 3-dioxygenase 1 (IDO1) is a rate-limiting enzyme in the kynurenine pathway and is highly overexpressed in malignant cells, leading to tryptophan exhaustion and kynurenine accumulation in the tumor milieu." (PMID 36080223, 2022). "The high expression frequency of both IDO1 and PD-L1 in EC suggests that therapies targeting only the PD-1/PD-L1 axis may be turned down in this tumor type due to IDO1 interference with immune cell function." (PMID 36119020, 2022). "Inhibition of IDO1 can activate antitumor immune responses in rodent tumor models." (PMID 36304470, 2022). "Controversially, kynurenine signaling through the AhR has been reported to promote the expression of the activating receptors NKp30, NKp46, perforin, and granzyme B in NK cells, which is supported by the observation that IDO1 inhibition impairs NK cell activity against tumor cells." (PMID 36713558, 2022). "Given that some forms of chemotherapy trigger ferroptosis, IDO1 may have multiple effects in controlling the outcomes of initial tumor growth by collectively suppressing T cell proliferation and ferroptosis." (PMID 35245456, 2022). "Alongside tumor cells, immunosuppressive cell metabolism was also of concern, an example being the upregulation of IDO1 by solid LUAD-derived mregDCs, which attenuated effector T cell responses by depleting tryptophan and producing the immunosuppressive metabolite kynurenine." (PMID 36138435, 2022). "According to a recent study, IDO1-expressing macrophages, DC, and tumor cells limit T cell growth." (PMID 35918736, 2022).
tumor (continued). "IDO1 plays a crucial role in tumor immunosuppression, and IDO1 may become a very attractive target for future anti-tumor molecular targeted therapy." (PMID 35681736, 2022). "A significant decrease in IDO1 expression can be observed in the tumor when inhibiting glutamine metabolism, accompanied by a robust reversal of the Kyn/Trp ratio, which led to the prediction that the increased IDO1 expression activates the immunosuppressive effect of MDSCs in TME." (PMID 35681736, 2022). "Surgically resected UPS samples were stained by immunohistochemistry (IHC) for the following: tumor-associated immune cells (CD3, CD8, CD163, CD20), immune checkpoints (stimulatory: OX40, ICOS; inhibitory: PD-L1, LAG3, IDO1, PD1), and the adenosine pathway (CD73, CD39)." (PMID 36313661, 2022). "As TDO appears to be up-regulated in more cancer types than has hitherto been assumed and appears to be a prognostic factor in patient survival, tumour tissues should be assessed for TDO2 in addition to IDO1 and IDO2 before embarking on mono or multiple therapies with inhibitors of these enzymes." (PMID 36286592, 2022). "Second, IDO1 is an innate immune regulator that converts Trp to Kyn in tumor microenvironments." (PMID 36545214, 2022). "This suggests that tumor cell associated IDO1 also has a tumor-promoting effect via a non-immune related function and therefore, apart from targeting IDO1 in the DCs, targeting tumor cell IDO1 might prove as a beneficial therapeutic strategy as well." (PMID 35997090, 2022). "Immunotherapy targeting IDO1 has been one of the focus areas in cancer biology, but lately studies have identified non-immune related functions of IDO1 leading to a paradigm shift with regard to IDO1 function in the context of tumor cells." (PMID 35997090, 2022). "Furthermore, IDO1 is involved in tumor neo-vascularisation, which is instead inhibited by IFN-gamma." (PMID 35408802, 2022). "This approach can also revert the immunosuppressive tumor IDO-1 and CTL responses." (PMID 36146572, 2022). "Interestingly, all tumor types showed strong correlation between IDO1 expression and CD3E and CD8A expressions." (PMID 35780226, 2022). "This study distinguished two profiles of tumor cells expressing IDO1." (PMID 36188218, 2022). "Stimulation with Jak-Stat-activating cytokines from the tumor microenvironment would enhance formation of Stat1-containing transcription factor complexes that lead to increased expression of type I and II interferon target genes including Ido1." (PMID 36185806, 2022). "Additional high expression of signatures involved in immune-checkpoint component and tumour immunity such as IDO1, IFN Gamma, PD-L1 and Tumour Inflammation Signature (TIS) as well as the genomic risk score were associated with High Ki672wk (OR 1·67–1·49, FDR<0·0001–0·0084, logistic regression)." (PMID 35985932, 2022). "Moreover, IDO1 plays an important role in tumor immunosuppression, and multiple inhibitors have been evaluated In clinical trials." (PMID 36077704, 2022). "Although some studies have shown that IDO1 is overexpressed in DLBCL, the role and mechanism of IDO1 activity in the tumor growth of DLBCL remain unclear." (PMID 35760783, 2022). "The compelling clinical evidence of elevated IDO1 expression impacting negatively on tumour immunity and patient survival has prompted many groups, to investigate novel tryptophan dioxygenase inhibitors for restoring tumour immunity." (PMID 36145311, 2022). "Several established targets have multiple clinical compounds in later stages of development across a variety of tumor types (e.g., IDO1, IDH1), while many earlier-phase studies are being initiated with first-in-class agents targeting metabolic nodes not yet explored (e.g., IACS-010759, opaganib)." (PMID 34981784, 2022). "The anti-tumor action of eicosapentaenoic acid contributed to IDO1 expression blockage." (PMID 35918736, 2022). "IDO1 is a rate-limiting metabolic enzyme overexpressed in T cells of tumor patients." (PMID 36387196, 2022).
tumor (continued). "In addition, we also confirmed that IDO1 was highly expressed in tumor tissues of NSCLC patients and negatively correlated with miR-760, which also verified our results from the side." (PMID 35872931, 2022). "Like TDO, IDO1 is expressed in numerous tumors in which it contributes to tumor immune escape." (PMID 36188218, 2022). "Targeted inhibition of IDO1 expression reverses tumor suppressive immune microenvironment." (PMID 36060659, 2022). "Of course, from a clinical standpoint, it will be hard to pin-point whether the observed anticancer effect is due to IDO1 inhibition in the immune cells or in the tumor cells." (PMID 35997090, 2022). "Indoleamine 2,3-dioxygenase 1 (IDO-1) is highly overexpressed on tumor cells." (PMID 36341334, 2022). "IDO1 is a cytosolic enzyme involved in the suppression of cytotoxic cells such as CD8 T cells and natural killer (NK) cells by depletion of tryptophan and the promotion of regulatory T cells, MDSCs and tumour-associated macrophages (TAMs)." (PMID 35454819, 2022). "In sample TJH08, the tumor areas commonly expressed high IDO1, low PD‐L1, and very low CTLA4." (PMID 35986392, 2022). "Over the last two decades, indoleamine 2,3-dioxygenase 1 (IDO1) has attracted wide interest as a key player in immune regulation, fostering the design and development of small molecule inhibitors to restore immune response in tumor immunity." (PMID 35409342, 2022). "Targeting IDO1-induced immunosuppressive mechanisms could represent a double-edged sword, since inhibiting IDO1 as a monotherapy could also lead to increased tumor development." (PMID 36405719, 2022). "Since aPD1 + YH29407 combination strategy showed the best anti-tumor effects than others, our findings suggest that an effective block of the IDO1 enzyme may form an ideal combination with an immune checkpoint inhibitor for cancer treatment." (PMID 36545214, 2022). "Moreover, it has been demonstrated that KYN treatment is able to regulate NK cells via STATs signalling pathways, blocking of IDO1 activity in tumour cells, restored NK cells’ cytolytic activity and receptors expression." (PMID 35682852, 2022). "The immunosuppressive enzyme indoleamine-2,3-dioxygenase-1 (IDO1) is involved in tumor formation." (PMID 36139584, 2022). "In addition, TDO2 has the function of transducing the tumor immune escape via the IDO1/TDO2–KYN–AhR signaling pathway." (PMID 36230866, 2022). "Finally, high levels of IDO1 induce IL-6 expression by MDSCs in an autocrine manner, leading to the recruitment of MDSCs at the tumor site." (PMID 35159363, 2022). "We detected Ido-1 expression as a widely diffuse staining in both tumor and stromal immune cells." (PMID 36419183, 2022). "Furthermore, TIGIT, LAG-3, HAVCR2 (TIM-3), and IDO1 are known as novel immune checkpoint targets that can suppress the activation of effector T lymphocytes, hence mediating a tumor immune escape mechanism." (PMID 35416526, 2022). "IDO1 can be overexpressed in tumor cells and dendritic cells, macrophages and endothelial cells." (PMID 35203450, 2022). "Furthermore, IDO1 is known to promote tumor neovascularization by modulating the expression of IFN-γ and interleukin (IL)-649." (PMID 36216827, 2022). "On the other hand, the reason may be that the exact regulatory mechanism of IDO1 in physiology and pathology or its impact on the tumor microenvironment are not well understood." (PMID 36304470, 2022). "Similarly, unique dose of recombinant kynureninase decreased Kyn levels and promoted higher levels of CD8 T cells in mice tumor models, thus modulating the effects of IDO1 and TDO2 within the TME." (PMID 35173722, 2022).